BID (BH3 interacting domain death agonist)
Description:
Induces caspases and apoptosis. Counters the protective effect of BCL2 (By similarity). [BH3-interacting domain death agonist p15]: Induces caspase activation and apoptosis. Translocates to mitochondria following cleavage and disrupts the outer mitochondrial membrane leading to the release of cytochrome c. [Isoform 1]: Induces ICE-like proteases and apoptosis. [Isoform 2]: Induces ICE-like proteases and apoptosis. [Isoform 3]: Does not induce apoptosis. [Isoform 4]: Induces ICE-like proteases and apoptosis.
Synonyms: FP497
Tractability: Small molecule: a structure with a bound ligand is known; a high-quality ligand is known. PROTAC: UniProt records ubiquitination sites on it; ubiquitination databases record sites on it; its protein half-life has been measured; a small molecule that binds it is known.
Gene: Protein-coding gene on chromosome 22 (17,734,138 to 17,774,770, reverse strand). Ensembl gene ENSG00000015475.
Subcellular location: Cytoplasm; Mitochondrion membrane; Mitochondrion outer membrane; Mitochondrion membrane (BH3-interacting domain death agonist p15); Mitochondrion membrane (BH3-interacting domain death agonist p13); Cytoplasm (Isoform 1); Cytoplasm (Isoform 3); Mitochondrion membrane (Isoform 2)
Subcellular location (Human Protein Atlas): Cytosol; Mitochondria
Pathways (Reactome):
Programmed Cell Death: Activation and oligomerization of BAK protein; Activation of BAD and translocation to mitochondria; Activation, myristolyation of BID and translocation to mitochondria; Activation, translocation and oligomerization of BAX; BH3-only proteins associate with and inactivate anti-apoptotic BCL-2 members
Gene Ontology:
Molecular function: protein binding; death receptor binding; ubiquitin protein ligase binding
Biological process: establishment of protein localization to membrane; hepatocyte apoptotic process; positive regulation of apoptotic process; positive regulation of extrinsic apoptotic signaling pathway; positive regulation of intrinsic apoptotic signaling pathway; positive regulation of protein-containing complex assembly; positive regulation of release of cytochrome c from mitochondria; release of cytochrome c from mitochondria; supramolecular fiber organization; apoptotic mitochondrial changes; extrinsic apoptotic signaling pathway via death domain receptors; neuron apoptotic process; signal transduction in response to DNA damage; cellular response to stress; intracellular signal transduction; protein-containing complex assembly; regulation of apoptotic process; regulation of apoptotic signaling pathway; regulation of intracellular signal transduction
Cellular component: cytoplasm; cytosol; mitochondrial membrane; mitochondrial outer membrane; mitochondrion; membrane
Genetic constraint (gnomAD): Loss-of-function variants: 19 observed, 17.9 expected, observed/expected ratio (o/e) 1.06, 90% interval 0.74 to 1.55. The upper end of that interval is the gene's LOEUF score, 1.55, which puts it in group 6 of 6, group 1 being the genes least tolerant of losing a copy. Missense variants: 226 observed, 258.24 expected, observed/expected ratio (o/e) 0.88, 90% interval 0.78 to 0.98. Synonymous variants: 108 observed, 103.38 expected, observed/expected ratio (o/e) 1.04, 90% interval 0.89 to 1.23.
Homologues: Orthologues: chimpanzee BID (100% identical), macaque BID (92% identical), dog BID (68% identical), mouse Bid (64% identical), pig BID (62% identical), rat Bid (61% identical), rabbit BID (57% identical), guinea pig BID (50% identical).
Diseases named in the same sentence as BID in open-access papers:
BID is named in the same sentence as 123 diseases in open-access papers, as found by Europe PMC text mining. Sharing a sentence is not in itself a finding about the gene and the disease. The quoted sentences say what the papers report.
breast carcinoma (18 papers, 2007 to 2024). "Evidence has shown that BID expression was decreased in various cancer types, including hepatocellular carcinoma and breast cancer, which further supports our findings." (PMID 39409902, 2024). "It has been demonstrated that silybin stimulated under-expression of Bcl-2 and overexpression of Bax and Casp-8, Casp-9, and BID in MCF-7 breast cancer cells." (PMID 34094034, 2021). "In addition, published studies had showed that the BID-overexpressing MDA-MB-468 breast cancer cells established in nude mice as xenografts were sensitive to the TTK inhibitors CFI-402,257 and BAY1217389." (PMID 37443114, 2023). "In the present research, a significantly increased expression of BAD gene was observed in both breast cancer cell lines and a significantly increased expression of BID gene in the MDA-MB-231 cell line under the influence of digested juice from young beetroot shoots." (PMID 37108053, 2023). "Lapatinib has been shown to inhibit the HER2 downstream signaling pathways RAF/MEK/ERK (ERK cascade) and PI3K/AKT/mTOR and lead to up-regulations of BIM (BCL-2–interacting mediator of cell death) and BID (BCL-2 antagonist of cell death) in HER2-overexpressed breast cancer cells." (PMID 24947902, 2014). "For example, in pancreatic and breast cancer cells, MYC expression products bind to and activate the promoters of the pro-apoptotic proteins BIM and BID, thereby facilitating the initiation of mitochondrial responses to apoptotic stimuli." (PMID 36527013, 2022). "Likewise, we confirmed the up-regulation of seven genes (BID, MRRL17, SH3PB5, MRRL49, TK1, TIMM10, and UNG) in rho0 cells and breast cancer cell lines." (PMID 21935467, 2011). "BID protein was significantly upregulated in colon cancer, lung cancer and breast cancer, but not in ovarian cancer (data not shown)." (PMID 17989776, 2007). "However, CD44 overexpression only slightly mitigated the levels of proapoptotic proteins BID and BAX, which were increased in MARCH8-GFP-overexpressing cells, suggesting that additional targets of MARCH8 are responsible for the alteration of proapoptotic signals in breast cancer cells." (PMID 34067416, 2021).
colon carcinoma (17 papers, 2007 to 2025). "A recent study showed that BID increased in brain tumor, gliomas, prostate cancer, ovarian cancer and colon cancer." (PMID 17989776, 2007). "Recently, BID was identified as independent prognostic variables in colon cancer." (PMID 33837652, 2021). "Moreover, BID was reported to be an independent prognostic gene in colon cancer." (PMID 31739630, 2019). "In colon tumors, immunohistochemical analysis demonstrated that regions of tumor that stained positive for pimonidazole, a hypoxia probe, displayed decreased levels of the proapoptotic Bcl family members, BH3-interacting domain death agonist (BID) and Bcl2-associated X (BAX)." (PMID 28383481, 2017). "In this sense, zosterabisphenone B induced apoptosis in HCT116 colon cancer cells increasing the levels of cleaved caspases, Poly (ADP-ribose) polymerase (PARP) and BH3 Interacting Domain Death Agonist (BID) proteins and a decrease in Bcl-2 and c-Myc proteins." (PMID 39942590, 2025). "A significant overlap was detected with several relevant gene families, including colon cancer progression (e.g., FN1, IGBP3, PLAUR and TIMP1; P=0.00052), tumour cell apoptosis (e.g., BID, TNFRSF21, PHLDA1 and NOTCH1; P=1.46 × 10–6) and cell proliferation (e.g., CTGF, SPP1, FOLR1 and SPARC)." (PMID 21119668, 2010). "In our knockdowns of BID in the human colon cancer cell line HCT116, no significant increase in the frequency of apoptotic cells was observed." (PMID 19119425, 2009).
melanoma (13 papers, 2014 to 2024). A malignant, usually aggressive tumor composed of atypical, neoplastic melanocytes. "The importance of the lexatumumab/BID interaction in human cancers was also reported in other papers, where lexatumumab induced apoptosis through the activation of BID in non-Hodgkin’s lymphoma, melanoma, and liver tumor cells." (PMID 38540271, 2024). "Like NOXA and BIM, knockdown of BID also enhanced melanoma resistance to the combination." (PMID 32764384, 2020). "In addition, GCNT2/I-branched glycan expressing melanoma cells displayed higher levels of proapoptotic genes, BID and BAX, and had lower expression of prosurvival genes, BCL-2 and BCL-XL." (PMID 30135430, 2018). "However, further studies are needed to investigate whether the elevated plasma CASP8 and BID are associated with an exacerbated apoptosis of peripheral blood mononuclear cells (PBMC) among these patients, similarly as in the case of melanoma patients." (PMID 37228491, 2023). "Researchers observed apoptosis associated with the activation of caspase-3, caspase-7, caspase-8 and caspase-9, as well as cleavage of BID and PARP, which is similar to our results of MZB activity against melanoma cells." (PMID 39057424, 2024). "BCL10 (3.84-fold), TRADD (2.71-fold), CYCS (2.51-fold), DIABLO (2.43-fold), BAD (2.36-fold), BID (2.17-fold), TNFSF8 (2.13-fold), TNFSF10 (2.11-fold), BAX (2.03-fold), and FAS (2.01-fold) were also proapoptotic genes highly upregulated in response to UA treatment in A-375 melanoma cells." (PMID 39473730, 2024).
glioma (11 papers, 2007 to 2024). A benign or malignant brain and spinal cord tumor that arises from glial cells (astrocytes, oligodendrocytes, ependymal cells). "Finally, we observed reduced expression of the pro-apoptotic Bcl2 family member, BH3 interacting domain death agonist (BID) in high-grade proneural gliomas, suggesting that loss of BID expression promotes survival of these high-grade tumors." (PMID 20838435, 2010). "BH3-interacting domain death agonist (BID) has been reported by immunohistochemical studies to be elevated in certain tumors such as cancers of the prostrate, colon, brain tumors such as gliomas and in lymphomas." (PMID 34830970, 2021). "We found that truncated BID (tBID) also was increased in TJY-16-treated U87 glioma cell." (PMID 26786523, 2016). "After constructing the risk model, we screened out the signature composed of five ATGs (BID, BAG1, PTK6, NRG3, MAP1LC3C) with the best prognosis prediction performance, indicating these five ATGs play an important role in glioma." (PMID 33768004, 2021). "MAPK3 and CX3CL1 were strongly positive; NFE2L2, HSP90AB1, and SUPT20H were moderately positive; and FKBP1B, BIRC5, NPC1, IKBKE, BID, and PTEN were weakly positive in glioma tissue relative to their expression levels in normal tissue." (PMID 33194668, 2020).
ovarian carcinoma (8 papers, 2007 to 2023). A malignant neoplasm originating from the surface ovarian epithelium. "According to a recent study, truncated BID controls the cisplatin response in ovarian cancer by triggering the mitochondrial apoptosis pathway." (PMID 37965453, 2023). "Under stress conditions, BCL2A1 accumulated and colocalized with mitochondria to suppress intrinsic cell apoptosis by interacting with the BH3-only subfamily BCL2 members HRK/BAD/BID in ovarian cancer cells." (PMID 34572804, 2021). "Protein expression levels of cleaved caspase-3, caspase-8, caspase-9, and PARP in the A2780 ovarian cancer cells markedly increased, whereas the expression of BID decreased after 20(S)-Rg3 treatment." (PMID 27051448, 2016). "The experimental results suggested that SH-6 could pass P38, mitogen-activated protein kinase (MARK), and Caspase-8-dependent BID decomposition pathways to induce apoptosis of ovarian cancer cell A2780." (PMID 35529935, 2022). "Moreover, BID also plays an inhibitory role in gastric cancer, ovarian cancer, pancreatic cancer and other cancers." (PMID 36060256, 2022). "Indeed, in prior studies Zhang and Jiang described that RhoA inhibits the hypoxia-induced apoptosis in chondrocytes and Khaider and colleagues demonstrated that the inhibition of BID expression by Akt leads to resistance to TRAIL-induced apoptosis in ovarian cancer cells." (PMID 36113340, 2022). "Co-expressed proteins like BID, NFKBP65, β-CATENIN, MAPK, and AKT play important role in ovarian cancer." (PMID 35840928, 2022).
colorectal cancer (7 papers, 2018 to 2025). A primary or metastatic malignant neoplasm that affects the colon or rectum. "Moreover, miR‐20a is also considered to act as a tumor promoter in colorectal cancer by increasing the levels of the pro‐apoptotic factor BID, which is associated with the tumor necrosis factor‐related apoptosis‐inducing ligand (TRAIL) sensitivity." (PMID 29266846, 2018). "With respect to BID truncation events, when HCT116 (human colorectal carcinoma) cells are treated with TRAIL in conjunction with erastin and artesumate, which induce ferroptosis, TRAIL classically enhances caspase-8 activation, and BID truncation increases in parallel." (PMID 41306288, 2025). "However, the role of CHMP2B, BID and CHMP6 in colorectal cancer have not been reported yet, which may provide new biomarkers for future research on the relationship between necrosis and colorectal cancer." (PMID 35783272, 2022).
lung cancer (7 papers, 2007 to 2024). A malignant neoplasm involving the lung. "This concept was recently validated in non–small cell lung cancer patients with amplification of Chr22q11, which harbors the BID gene locus." (PMID 39475598, 2024). "In lung cancer, evidence sentences were also found for all but three genes (BID, NPY, TPI)." (PMID 34653225, 2021). "However, another TRAIL-resistant non-small human lung cancer A549 cell line has been shown to get TRAIL sensitivity upon expression of BID from pDNA vector." (PMID 25326334, 2014). "We also demonstrated that high doses of PL elicit a caspase cascade in human and murine lung cancer cells, but not in normal lung epithelial cells, in which caspase 3, caspase 8 and BID are activated." (PMID 17262078, 2007).
thyroid cancer (7 papers, 2014 to 2024). "Studies have found that BID is associated with the survival of thyroid cancer and clear-cell renal cell carcinoma." (PMID 33768004, 2021). "BID is over-expressed in thyroid cancer and associated with patient prognosis." (PMID 31626592, 2019). "Furthermore, we investigated the possible correlations of hsa-miR-331-5p (MIMAT0004700) and the BID mRNA target (ENSG00000015475) across the thyroid cancer tumors deposited in TCGA-THCA, finding an inverse association (r = −0.11, p = 1.1 × 10−2) between miR-331-5p and BID." (PMID 38540271, 2024). "BID is significantly overexpressed in thyroid cancer patients, where it is inversely correlated with miR-331-5p." (PMID 38540271, 2024). "In previous studies, BID, FBXW7, and GPX4 had already been found to be significant in thyroid cancer, whereas the role of AKR1C3 and MAP3K5 in the development and progression of thyroid cancer has not yet been reported." (PMID 35741758, 2022). "In thyroid cancer cells, Gal-3 was reported to induce PI3K-Akt pathway in which acts as pro-survival signaling and inhibits pro-apoptotic sensors such as BID." (PMID 25393982, 2014). "AKR1C3, BID, FBXW7, GPX4, and MAP3K5 were independent prognosis signatures of thyroid cancer." (PMID 35741758, 2022). "Moreover, Gunda and colleagues also suggested that BID is one of the genes responsible for the apoptotic effects of lexatumumab, a monoclonal antibody that specifically activates TRAIL-receptor 2, inducing cell death in thyroid cancer cells." (PMID 38540271, 2024).
gastric cancer (6 papers, 2014 to 2025). A primary or metastatic malignant neoplasm involving the stomach. "The study objective was to assess the expression of Bcl-2 and BID in gastric cancer cells in correlation with chosen clinicopathological parameters, presence of Helicobacter pylori infection, and patients' survival." (PMID 24741635, 2014). "The correlations between the expression levels of Bcl-2 and BID in gastric cancer cells were found to be statistically insignificant." (PMID 24741635, 2014). "We found positive expression of Bcl-2 in 55.7% and BID in 53.6% of patients with gastric cancer." (PMID 24741635, 2014). "In AGS gastric cancer cells, we observed consistent 1.3-8-fold up-regulation of pro-apoptotic genes such as BAD, BAX, BID, and FAS after control lettuce and lettuce fortified with organic iodine, as compared to negative control." (PMID 36296971, 2022).
leukaemia (6 papers, 1987 to 2022). "In all leukemia samples treated with α-bisabolol, BID was found to be expressed in a full-lenght form that was suitable for binding to α-bisabolol." (PMID 21510902, 2011). "Moreover, activating endogenous BID can be clinically relevant for therapy to kill venetoclax‐resistant leukaemia cells lacking active BAX and BAK." (PMID 34931711, 2022). "Additionally, we demonstrate the therapeutic potential of tBID‐mediated MOMP in venetoclax‐resistant Nalm6 leukaemia cells lacking active BAX and BAK, in which TRAIL treatment efficiently induces BID‐dependent apoptosis." (PMID 34931711, 2022).
prostate carcinoma (6 papers, 2007 to 2025). A carcinoma that arises from epithelial cells of the prostate gland. "The expression of C-terminal part of cleaved BID was sufficient to induce apoptosis in prostate cancer cells." (PMID 33668112, 2021). "Several publications assessed death receptors signaling that was activated by FAS, TNF-α and TRAIL ligands in prostate cancer cells, and reported on the role of BID cleavage in defining an apoptosis decision." (PMID 33668112, 2021). "Another study showed that MSCs, which expressed anti-PSA antibody and BH3-interacting domain death agonist (BID, a member of Bcl-2 protein family) fusion protein, could be used to treat prostate cancer." (PMID 36104733, 2022). "Upon incubation with 9F7-F11, we observed BID cleavage and BIM expression also in DU145 prostate cancer cells, which are BAX-deficient but express BAK that could replace BAX to induce caspase-9 activation." (PMID 31443721, 2019).